LDLRAD4-AS1 (LDLRAD4 antisense RNA 1)
Gene: Long non-coding RNA gene on chromosome 18 (13,419,421 to 13,427,480, reverse strand). Ensembl gene ENSG00000267690.
Diseases named in the same sentence as LDLRAD4-AS1 in open-access papers:
LDLRAD4-AS1 is named in the same sentence as 1 disease in open-access papers, as found by Europe PMC text mining. Sharing a sentence is not in itself a finding about the gene and the disease. The quoted sentences say what the papers report.
colorectal cancer (1 paper, 2023). A primary or metastatic malignant neoplasm that affects the colon or rectum. "In contrast, LDLRAD4 antisense RNA 1 (LDLRAD4-AS1) has been reported to exhibit up-regulation in colorectal cancer (CRC) tissue." (PMID 37761849, 2023).